ONECUT3 (one cut homeobox 3)
Description:
Transcriptional activator. Binds the consensus DNA sequence 5'-DHWATTGAYTWWD-3' on a variety of gene promoters such as those of HNF3B and TTR (By similarity).
Synonyms: OC3
Tractability: No criterion of Open Targets' tractability assessment is met for any kind of drug.
Gene: Protein-coding gene on chromosome 19 (1,753,506 to 1,780,988, forward strand). Ensembl gene ENSG00000205922.
Subcellular location: Nucleus
Subcellular location (Human Protein Atlas): Nucleoplasm
Pathways (Reactome):
Developmental Biology: Regulation of gene expression in early pancreatic precursor cells; Regulation of gene expression in late stage (branching morphogenesis) pancreatic bud precursor cells
Gene Ontology:
Molecular function: protein binding; sequence-specific double-stranded DNA binding; DNA-binding transcription factor activity, RNA polymerase II-specific; RNA polymerase II cis-regulatory region sequence-specific DNA binding; DNA binding; DNA-binding transcription activator activity, RNA polymerase II-specific; DNA-binding transcription factor activity; RNA polymerase II transcription regulatory region sequence-specific DNA binding
Biological process: regulation of transcription by RNA polymerase II; positive regulation of transcription by RNA polymerase II
Cellular component: nucleoplasm; chromatin; nucleus; transcription regulator complex
Genetic constraint (gnomAD): Loss-of-function variants: 13 observed, 8.5 expected, observed/expected ratio (o/e) 1.53, 90% interval 0.96 to 1.93. That is too few expected variants to judge how well the gene tolerates losing a copy. Missense variants: 558 observed, 382.37 expected, observed/expected ratio (o/e) 1.46, 90% interval 1.36 to 1.57. Synonymous variants: 292 observed, 184.02 expected, observed/expected ratio (o/e) 1.59, 90% interval 1.44 to 1.75.
Homologues: Orthologues: macaque ONECUT3 (99% identical), dog ONECUT3 (95% identical), pig ONECUT3 (95% identical), rat Onecut3 (92% identical), mouse Onecut3 (92% identical), chimpanzee ONECUT3 (88% identical), tropical clawed frog onecut3 (61% identical), zebrafish onecut3b (59% identical), zebrafish onecut3a (58% identical), Drosophila melanogaster onecut (42% identical), Caenorhabditis elegans ceh-48 (33% identical), Caenorhabditis elegans ceh-38 (30% identical), and 3 more. Paralogues in human: ONECUT1 (54% identical), ONECUT2 (54% identical).
Diseases named in the same sentence as ONECUT3 in open-access papers:
ONECUT3 is named in the same sentence as 17 diseases in open-access papers, as found by Europe PMC text mining. Sharing a sentence is not in itself a finding about the gene and the disease. The quoted sentences say what the papers report.
myelodysplastic syndrome (2 papers, 2024 to 2025). A clonal hematopoietic disorder characterized by dysplasia and ineffective hematopoiesis in one or more of the hematopoietic cell lines. "Furthermore, in myelodysplastic syndromes, overexpression of ONECUT3 causes chromosomal passenger complex (CPC) dysregulation and mitotic defects that affect cell mitosis." (PMID 40032849, 2025). "Ectopic expression of the transcription factor ONECUT3 is a driver of chromosomal abnormalies in myelodysplastic syndromes." (PMID 38386414, 2024).
pancreatic cancer (2 papers, 2023 to 2025). "In pancreatic cancer, ONECUT3 can promote the process of glycolysis by regulating pyruvate dehydrogenase kinase (PDK)." (PMID 40032849, 2025). "Similar to our findings, research in pancreatic cancer has shown that ONECUT3 affects tumor glycolysis and inhibits CD8 + T cell infiltration, as well as the efficacy of anti-PD-1 therapy." (PMID 40032849, 2025).
acute myeloid leukemia (1 paper, 2024). Acute myeloid leukemia (AML) is a group of neoplasms arising from precursor cells committed to the myeloid cell-line differentiation.
cognitive deficits (1 paper, 2023). "Cumulatively, these data suggest that Onecut3+ neurons in the lateral hypothalamus form extrahypothalamic projections towards brain areas that are Trhr+, and associated with learning and memory, an arrangement compatible with cognitive deficits upon congenital hypothyroidism." (PMID 37029761, 2023).
colon cancer (1 paper, 2025). "The knockdown of either ONECUT3 or HDAC6 in colon cancer cells led to a marked increase in the acetylation level of HIF-1α." (PMID 40032849, 2025). "Subsequently, immunohistochemical staining was performed to determine the expression of ONECUT3 in both colon cancer tissues and adjacent normal tissues." (PMID 40032849, 2025). "The results demonstrated a significant decrease in the ECAR, an indicator of glycolysis, following ONECUT3 knockdown and a substantial increase after ONECUT3 overexpression in colon cancer cells." (PMID 40032849, 2025). "We conducted an extracellular acidification rate (ECAR) assay in colon cancer cells to examine the regulatory role of ONECUT3 in glycolysis." (PMID 40032849, 2025). "Initially, we detected the mRNA and protein expression of ONECUT3 in six colon cancer cell lines (CACO2, COLO205, HT29, LOVO, SW480, SW620) and a regular colon epithelial cell line (NCM460)." (PMID 40032849, 2025). "Further experiments showed that knocking down ONECUT3 inhibited the proliferation and glycolysis of colon cancer cells, while overexpressing ONECUT3 enhanced these processes." (PMID 40032849, 2025). "Therefore, ONECUT3 was selected as the key gene to investigate the glycolytic pathway in colon cancer." (PMID 40032849, 2025). "Additionally, the glycolysis inhibitor 2-DG mitigated the proliferative effects of ONECUT3 overexpression in colon cancer cells." (PMID 40032849, 2025). "We found that ONECUT3 was significantly upregulated in the high-glycolytic group according to the TCGA database, and its expression was notably higher in colon cancer tissues compared to adjacent non-cancerous tissues." (PMID 40032849, 2025). "However, the subsequent experimental results showed that knockdown or overexpressing ONECUT3 in colon cancer cells did not affect the mRNA or protein expression of HIF-1α." (PMID 40032849, 2025).
glioblastoma (1 paper, 2024). The most malignant astrocytic tumor (WHO grade IV). "Next, we opted for a glioblastoma cell line (U-251) to test the extreme possibility that ONECUT3 could induce a cell identity switch (glia → neuron)." (PMID 39366958, 2024).
lung adenocarcinoma (1 paper, 2024). A carcinoma that arises from the lung and is characterized by the presence of malignant glandular epithelial cells. "High ONECUT3 expression is also frequent and associated with a worse prognosis in different cancer data sets, e.g., data sets for lung adenocarcinoma (LUAD), lung squamous cell carcinoma (LUSC), adrenocortical carcinoma (ACC), and kidney renal clear cell carcinoma (KIRC)." (PMID 38386414, 2024).
lung carcinoma (1 paper, 2022).
myeloid neoplasm (1 paper, 2024). Proliferation of myeloid cells originating from a primitive stem cell. "The role of ONECUT3 in cancer is not well defined, and studies of ONECUT3 activity in myeloid neoplasms are limited." (PMID 38386414, 2024).
periodontitis (1 paper, 2022). An acute or chronic inflammatory process that affects the tissues that surround and support the teeth. "Furthermore, 12 hub genes ranked by the top 10% genes with high degree connectivity and five TFs, including SRF, CNOT4, SIX6, SRRM3, NELFA, and ONECUT3, were identified and might play crucial roles in the molecular pathogenesis of periodontitis." (PMID 35397550, 2022).
cancer (3 papers, 2017 to 2024). A tumor composed of atypical neoplastic, often pleomorphic cells that invade other tissues. "To date, research on ONECUT3 has focused on the physiological regulation of embryo development, while the roles of ONECUT3 in cancer remain poorly understood." (PMID 38386414, 2024). "We found that the abundance of PDAC stemness negatively influenced the infiltration of NK cells and identified the transcription factor ONECUT3 enriched in PDACs with high stemness index scores and Pan-cancer Stemness Signature levels." (PMID 37875589, 2023). "Given that chromosomal instability confers multidrug resistance in cancer, we sought to investigate whether ONECUT3 expression would affect the sensitivity of cells to chemotherapeutic drugs." (PMID 38386414, 2024). "Our findings suggest that the regulation of inhibitory signals for NK cell activation by ONECUT3 may protect the rare population of cancer stem cells from robust anti-tumour immunity during distant metastasis or local recurrence." (PMID 37875589, 2023). "ONECUT3-mediated prostanoid metabolism may regulate cancer stemness and immune evasion in PDAC." (PMID 37875589, 2023).
tumor (3 papers, 2022 to 2025). "Specifically, higher ONECUT3 expression was associated with microsatellite instability status, larger tumor diameters, and higher Ki-67 levels." (PMID 40032849, 2025). "The upregulation of ONECUT3 in CRC facilitates tumor growth by enhancing the transcriptional activity of HIF-1α through HDAC6-mediated deacetylation." (PMID 40032849, 2025). "The results showed a significant correlation between the expression of ONECUT3 and microsatellite status, tumor diameter, and Ki-67 level." (PMID 40032849, 2025). "We utilized a nude mouse subcutaneous transplantation tumor model to verify the effect of ONECUT3 on tumor growth in vivo." (PMID 40032849, 2025). "Intriguingly, the levels of ONECUT3 expression were the highest in the pancreatic progenitor tumours among the four subtypes of PDAC." (PMID 37875589, 2023). "Functionally, silencing ONECUT3 reverses the Warburg effect and suppresses tumor growth." (PMID 40032849, 2025). "Importantly, ONECUT3 promotes tumor growth in a glycolysis-dependent manner through hypoxia-inducible factor 1α (HIF-1α)." (PMID 40032849, 2025). "Given the importance of HIF-1α in aerobic glycolysis, we hypothesized that ONECUT3 might regulate tumor glycolytic metabolism through HIF-1α." (PMID 40032849, 2025). "We investigated whether ONECUT3 could influence the proliferation of CRC cells through the Warburg effect, which is known to enhance tumor cell proliferation." (PMID 40032849, 2025). "In this study, we demonstrated that ONECUT3 mediates HIF-1α deacetylation through histone deacetylase 6 (HDAC6), leading to the activation of HIF-1α transcription and its downstream glycolysis-related genes, thereby enhancing the Warburg effect and promoting tumor growth in CRC." (PMID 40032849, 2025).
ONECUT3 also shares sentences with these, for which no sentence is quoted: colorectal cancer (2 papers); adenoma (1); congenital hypothyroidism (1); lung squamous cell carcinoma (1); trachoma (1).